IL17A (interleukin 17A)
Diseases named in the same sentence as IL17A in open-access papers (continued):
Sharing a sentence is not in itself a finding about the gene and the disease.
pulmonary fibrosis (continued). "In order to clarify the roles of Th17 cells and IL-17A+ γδ T cells in this model of pulmonary fibrosis, we utilized a cell-type specific deletion of the mTOR signaling protein raptor to selectively block generation of Th17 cells." (PMID 27649073, 2016). "Our work reveals the important role that IL-17A+ γδ T cells play in promoting the development of pulmonary fibrosis." (PMID 27649073, 2016). "Previous work investigating the role of IL-17A-producing cells in pulmonary fibrosis has utilized the intratracheal bleomycin model." (PMID 27649073, 2016). "While Th17 cells have been implicated in promoting the development of fibrosis through production of IL-17A, γδ T cells have been found to ameliorate lung fibrosis." (PMID 27649073, 2016). "Our study reveals the key role of IL-17A+ γδ T cells in promoting the development of pulmonary fibrosis." (PMID 27649073, 2016). "Prior studies have found that both Th17 cells and γδ T cells are upregulated in animal models of pulmonary fibrosis and produce the cytokine IL-17A." (PMID 27649073, 2016). "The role of Th17 cells and their secretion of IL-17 (IL-17A) in pulmonary fibrosis has been previously demonstrated by our group as well as others." (PMID 25888222, 2015). "IL-17A plays a crucial role in the development and progression of both acute and chronic inflammation-induced pulmonary fibrosis." (PMID 26223249, 2015). "In patients with idiopathic pulmonary fibrosis (IPF), IL-17A cooperates with and cross-regulates IL-1β, and the interaction of these cytokines contributes critically to neutrophil recruitment and lung fibrosis and possibly to liver fibrosis." (PMID 25590646, 2015). "He mentioned that pulmonary fibrosis induced by chronic allergen exposure is Il-13 dependent, while bleomycin-induced fibrosis is mediated by Il-17A produced by CD4+ T cells and γδ+T cells." (PMID 24484528, 2014). "In the model of bleomycin-induced lung injury, IL-17A gene knockout mice showed a milder lung fibrosis than gene wild-type mice." (PMID 24744681, 2014). "IL-17A has been shown to participate in the development of skin and lung fibrosis induced by bleomycin in mice." (PMID 24289089, 2013). "More recently, a study showed that bleomycin and IL-1β-mediated pulmonary fibrosis was IL-17A dependent." (PMID 21858022, 2011). "While this study was being finalized, Wilson and colleagues published a study reporting a critical role for IL-17A in BLM- or IL-1β-induced lung fibrosis." (PMID 21858022, 2011). "Hence, these results revealed that neutrophils and Th17 cells are critical for the PD-induced aggravation of pulmonary fibrosis and that Th17 cells regulate neutrophils via IL-17A." (PMID 40496020, 2025). "Therefore, IL-17A contributes to C. acnes-induced sarcoidosis-like inflammation in both granulomatosis inflammation and disease progression to pulmonary fibrosis." (PMID 40724901, 2025). "Furthermore, our data verified that Th17 cells recruited neutrophils via IL-17A to aggravate pulmonary fibrosis." (PMID 40496020, 2025). "Studies have shown that 4 weeks of moderate-intensity aerobic exercise suppresses the expression of TGF-β1 and inflammatory pathways TLR4/TNF-α and SRB/NLPR3, which, in turn, suppresses the expression of macrophage-derived IL-17A, thereby ameliorating silica-induced pulmonary fibrosis." (PMID 39796197, 2025). "IL-17A levels are increased in BAL of patients with idiopathic pulmonary fibrosis." (PMID 37744375, 2023). "Also, in the overall accepted bleomycin or IL-1β-induced pulmonary fibrosis, both IL-23 and IL-17A play a significant role in this context." (PMID 37685766, 2023). "Several murine fibrosis model studies showed that the progression of pulmonary fibrosis could be slowed down by inhibiting IL-17A." (PMID 37307262, 2023). "In addition, the same situations of inflammation, neutrophilia, and pulmonary fibrosis develop after IL-17A production following IL-1β treatment." (PMID 38202170, 2023).
pulmonary fibrosis (continued). "Elevated levels of IL-6 and IL-17 have been related to pulmonary fibrosis, and the elements of the IL-17A signaling cascade may serve as possible treatment targets for the treatment of fibroproliferative lung disorders." (PMID 37858084, 2023). "Finally, IL-17A also worsens type II alveolar epithelial cells’ ability to maintain mitochondrial homeostasis, which contributes to lung fibrosis." (PMID 37858084, 2023). "In pulmonary fibrosis, in vitro experiments have demonstrated that treatment with an anti-interleukin-23-specific antibody attenuated airway inflammation and reduced fibrosis by blocking interleukin-17A and -22 release." (PMID 37685766, 2023). "Together, these results indicate that the antifibrotic effects of daphnetin on BLM-induced lung fibrosis may be attributed to the inhibition of IL-17A production and Th17 differentiation." (PMID 38132116, 2023). "Consequently, the IL-17A antibody decreased bleomycin-induced pulmonary fibrosis as evidenced by decreased fibrosis-related Szapiel’s score, Ashcroft scores and reduced collagen deposition." (PMID 36564791, 2022). "Antagonizing IL-17A to ameliorate C9 cascade could provide new strategies to abrogate lung fibrosis." (PMID 35603223, 2022). "first suggested in their studies that IL-17A actively induce C9 cascade in lung fibrosis." (PMID 35603223, 2022). "In BLM-induced skin and lung fibrosis models, IL-17A and Th17 cells could promote the proliferation and cytokines secretion of fibroblasts, thereby promoting the process of fibrosis." (PMID 35396386, 2022). "IL-17A is indicated to have profibrotic role in mouse models of lung fibrosis." (PMID 35603223, 2022). "Furthermore, in the murine IPF model, BAFF expression and lung fibrosis were IL- 1β- and IL-17A-dependent." (PMID 33924683, 2021). "Moreover, this work not only validated the important role of IL-17A, but also supports the claim that IL-36R is a contributing factor in lung fibrosis." (PMID 32899668, 2020). "Importantly, studies in experimental pulmonary fibrosis have shown a neutrophil dependent IL‐17A pathway in the induction of lung fibrosis." (PMID 32567222, 2020). "Furthermore, IL-17A was observed to promote the progression of lung fibrosis by regulating the interaction between inflammatory responses and autophagy." (PMID 32724454, 2020). "In line with this, the blockade of IL-17A production by IL-38 implies that Th17 T cell activation may be an important governing element of IL-36 induced lung fibrosis." (PMID 32899668, 2020). "These discrepancies might depend on the fact that none of the mouse models that have been used to investigate the role of IL-17A in skin and lung fibrosis in vivo recapitulate the complete features of SSc." (PMID 32174912, 2020). "Thus, it was not essential for development of bleomycin-induced pulmonary fibrosis, although we expected IL-17C to contribute to development of T cell-independent IL-17A-mediated bleomycin-induced pulmonary fibrosis." (PMID 30356086, 2018). "Indeed, IL-17A promotes pulmonary fibrosis by attenuating autophagy via activating the PI3-kinase/GSK3b/Bcl-2 signaling cascade in lung epithelial cells." (PMID 28039485, 2017). "We and others demonstrated that bleomycin induces pulmonary fibrosis in an IL-17A dependent manner." (PMID 28039485, 2017). "Additionally, in idiopathic pulmonary fibrosis, the lung expresses high levels of IL-1β, IL-17A, and IL-23." (PMID 29254155, 2017). "Because neutralizing IL-17A attenuates bleomycin-induced pulmonary fibrosis by promoting the resolution of inflammatory response, we therefore hypothesized that blocking the biological function of IL-17A might have therapeutic benefits against liver fibrosis." (PMID 28039485, 2017).
pulmonary fibrosis (continued). "Impairment of autophagy by TGF-β1 or IL-17A promoted fibrogenesis in pulmonary fibrosis, while autophagy activation via IL-17A blockage decreased the production of collagen, attenuated fibrosis, and increased survival in the murine model of bleomycin-induced fibrosis." (PMID 26078809, 2015). "Furthermore, IL-17A has a critical role in the generation of bleomycin-induced pulmonary fibrosis, which is dependent on TGF-β, suggesting codependent roles for IL-17A and TGF-β in the pathogenesis of fibrosis." (PMID 26635811, 2015). "However, IL-17A contribution to idiopathic or drug-induced pulmonary fibrosis can be summarized as TGF-β dependent and TGF-β independent roles." (PMID 24744681, 2014). "The expression of RORγt and IL-17A increased significantly during the inflammatory stage in silica induced lung fibrosis, which confirmed other results that Th17 response increased in the silica induced lung fibrosis." (PMID 22615967, 2012). "Another study described how IL-17A may regulate the expression and/or proinflammatory properties of IL-22 in pulmonary fibrosis but did bot analysed the link between IL-1β, IL-23and IL-17." (PMID 21858022, 2011). "It should be noticed that IL-17A has been shown to participate in an IL-1-dependent manner to the development of bleomycin-induced mouse lung fibrosis and IL-17 may directly stimulate collagen synthesis in rodent fibroblasts." (PMID 21996293, 2011). "Importantly, decreased Htr4 expression might contribute to hypoalveolarization, and the elevated Il-17a expression might be responsible for prenatal DINP exposure-induced pulmonary fibrosis in male offspring." (PMID 42071020, 2026). "Here, our results demonstrated that PD aggravated BLM-induced pulmonary fibrosis in mice and that the ectopically colonized PD pathogen Pg promoted the infiltration of neutrophils and Th17 cells, and Th17 cells regulated neutrophils via IL-17A to exacerbate pulmonary fibrosis." (PMID 40496020, 2025). "However, whether and how IL-17A mediates the transition from acute to chronic lung injury remain unknown in the context of the progression of pulmonary fibrosis induced by sub-chronic PM exposure." (PMID 35739565, 2022). "Importantly, IL-17A may exert the profibrotic role through TGF-β-dependent or -independent mechanisms in the progression of xenobiotics-induced pulmonary fibrosis." (PMID 35739565, 2022). "Therefore, the increased IL-17A also plays a critical role in pulmonary fibrosis." (PMID 31309122, 2019). "Indeed, the increased levels of IL-17A in multiple exposures to A. suum might reflect the intense and chronic inflammation in the tissue remodeling, as is well demonstrated in a model of pulmonary fibrosis." (PMID 26814713, 2016). "Additionally, our data indicates that IL-17A+ γδ T cells alone are sufficient to cause pulmonary fibrosis in the absence of Th17 cells." (PMID 27649073, 2016). "Thus, he concluded that both Il-13 and Il-17A are important mediators of pulmonary fibrosis." (PMID 24484528, 2014). "The relative contribution of IL-17A and F in lung fibrosis was still unknown." (PMID 21858022, 2011). "Importantly, IL-23p19 and IL-17A are upstream of TGF-β1 the central mediator of lung fibrosis." (PMID 21858022, 2011). "Moreover we identified γδ T cells as the major source of early IL-17A, providing a new mechanism whereby IL-1 and IL-23 may mediate pulmonary fibrosis." (PMID 21858022, 2011). "In mice treated with BLM, atRA attenuated the upregulation of IL-17A, IL-10, IL-6, EphA2, EphriA1, PI3K 110γ, Akt, IL-6, TNF-α, and TGFβ1, which reduced pulmonary fibrosis and significantly alleviated lung fibrosis." (PMID 40508111, 2025). "In a mouse model of lung fibrosis, Lactobacillus supplementation significantly downregulated collagen 1 A production, inactivated the IL-17A and TGF-β1 signalling pathways, and alleviated bleomycin-stimulated lung fibrosis." (PMID 39796631, 2025).
pulmonary fibrosis (continued). "In the model of IL-17A-knockout C57BL/6 mice, the heat-killed C. acnes is able to induce sarcoidosis-like granulomas and even pulmonary fibrosis." (PMID 40724901, 2025). "Counterintuitive findings from another study showed that exogenous administration of the AHR ligand FICZ ameliorated pulmonary fibrosis, presumably by augmenting numbers of FoxP3+ Tregs and decreasing IFN-γ+ CD4+ and IL-17A+ γδ+ T cells." (PMID 39964756, 2025). "Mechanistic experiments first recognized that PD-1+CD4+ T cells can promote pulmonary fibrosis and TGF-β production mainly through IL-17A, where T helper 17 (Th17) cells are the main CD4+ T cell subset expressing TGF-β." (PMID 38263193, 2024). "In an in vivo animal experiment, blocking PD-1 expression significantly reduced the expression of STAT3, IL-17A, and TGF-β on Th17 cells, thereby reducing the production of type I collagen by fibroblasts and attenuating lung fibrosis." (PMID 38263193, 2024). "These lipid-lowering agents attenuated airway hyperresponsiveness, macrophages in BALF, lung fibrosis, serum leptin, free fatty acids, TGF-β1, IL-1β, IL-6, and IL-17a in the lung." (PMID 38762465, 2024). "We also assessed IL-17A and TGF-β1 production by sex, as CD4+ T cells promote pulmonary fibrosis through the STAT3-medicated production of IL-17A and TGF-β1." (PMID 36899902, 2023). "In the early stages of the fibrosis process, BLM increases the production of IL-17A in CD4+ T cells and γδT cells, which contributes to the development of lung fibrosis." (PMID 38132116, 2023). "Our findings clearly demonstrated that daphnetin inhibited IL-17A and EMT both in vitro and in vivo, thereby protecting against BLM-induced pulmonary fibrosis." (PMID 38132116, 2023). "IL-17 was detected in the sera of BLM-treated mice as well as patients with IPF, and lung fibrosis was inhibited by IL-17A antibody treatment." (PMID 36674533, 2023). "Estrogen clearly augments the development of lung fibrosis; yet, the binding of ERα to the STAT3 promoter shifts profibrotic cytokine expression away from proinflammatory phenotypes mediated by IL-17A to immunosuppressive phenotypes mediated by TGF-β1." (PMID 36899902, 2023). "To explore how T cells increase collagen production of NIH/3T3 cells, we assessed expressions of IL-17A and IFN-γ, two other mediators of pulmonary fibrosis." (PMID 36564791, 2022). "Collectively, these findings indicate that MDSCs recruited by activated IL-17A might work in synchrony with the activation of fibroblasts to perturb the balance between collagen synthesis and clearance, leading to the initiation of pulmonary fibrosis in response to PM exposure." (PMID 35739565, 2022). "For example, the favorable group for pulmonary fibrosis includes IL-1β, IL-4, IL-6, IL11, IL-13, IL-17A, IL-15, and IL-33; in contrast, the other group with anti-fibrotic function has IL-7, IL-10, IL-12, and IL-27." (PMID 35082682, 2021). "IL-17A, produced by CD4+ and γδ+ T cells, has been confirmed to induce significant neutrophilia and pulmonary fibrosis after exposure to bleomycin." (PMID 31309122, 2019). "Studies using neutralizing Abs and KO mice showed that the elimination of IL-17A and/or TGF-β led to a significant reduction in BLM-induced pulmonary fibrosis." (PMID 22708497, 2012). "Importantly, IL-23p19 and IL-17A are upstream of the expression of TGF-β1 the central mediator of lung fibrosis suggesting that innate IL-17A from γδ T cells might promote the commitment towards an inflammatory Th17 phenotype through induction of TGF-β1 in an IL-6 rich environment." (PMID 21858022, 2011). "We further substantiated this hypothesis in vitro by directly inducing fibroblast differentiation using CD4+PD-1+ T cells, likely through TGF-β1 and IL-17A overproduction, as demonstrated in our observations of BLM-induced pulmonary fibrosis in murine models." (PMID 41494735, 2026).
pulmonary fibrosis (continued). "Thus, moderate-intensity aerobic exercise (60 min/day, five times/week for 4 weeks) attenuates silica-induced lung fibrosis by inhibiting the TLR4-TNF-α, SRB-NLPR3, TGF-β1, and IL-17A/CXCL5/CXCR2 signaling pathways." (PMID 39796197, 2025). "Reasonably, our study showed that PD did not aggravate pulmonary fibrosis after neutrophil depletion or IL-17A depletion." (PMID 40496020, 2025). "It has been shown that IL-17A, the main cytokine of type 17 immunity, is able to induce EMT through the production of TGF-β, direct stimulation of fibroblasts and fibrocytes, and autophagy inhibition that otherwise would protect against lung fibrosis." (PMID 40508111, 2025). "In one report of pulmonary fibrosis, IL-17A–producing δγ T cells accentuate fibrosis independent of Th17 cells." (PMID 37159282, 2023). "IL-17A, as a predominant upstream regulator of IL-17 signaling pathway promotes the progression of chronic inflammation-related pulmonary diseases, such as COPD and pulmonary fibrosis." (PMID 35739565, 2022). "Interestingly, blockading the PD-1 pathway significantly decreased STAT3, IL-17A, and TGF-β expression levels on Th17 cells, subsequently reducing collagen I production from fibroblasts and attenuating lung fibrosis in a murine model." (PMID 36544757, 2022). "No definitive evidence can prove the role of IL-17A in lung fibrosis progression involved in SSc patients.The dichotomous nature of IL-17 lies in that it is pro-fibrotic in animal models while having a dual pro-inflammatory and anti-fibrotic role in humans." (PMID 35603223, 2022). "However, the researchers found IL-17A/IL-17RA axis was necessary for the production of TGF-β, a critical mediator of tissue remodeling and collagen deposition in pulmonary fibrosis." (PMID 33789737, 2021). "While Th17 cells also produce the pro-fibrotic cytokine IL-17A, our data indicates that these cells are not necessary for generation of pulmonary fibrosis in this model." (PMID 27649073, 2016). "Recent reports propose IL-17A as an important mediator in non-renal fibrosis, bleomycin induced pulmonary fibrosis and hepatic fibrosis induced by either cholestasis or hepatotoxic agents." (PMID 24454873, 2014). "In accordance with these observations, we noted that a recruitment of lung CD4+ T lymphocytes, T regs and Th17 cells (IL-17A), but not CD8+ T or NK cells (not shown), was associated with lung fibrosis in WT animals after silica treatment." (PMID 25050810, 2014). "After silica stimulation, the expression and secretion of IL-17A were enhanced as well as the expression of ROR-γt, which was consistent with the study in vivo showing that Th17 response increased in the silica-induced lung fibrosis." (PMID 24692850, 2014). "Altogether, these studies suggest that IL-17A may play an important role in both pathological processes of RILI: radiation pneumonitis and pulmonary fibrosis." (PMID 24744681, 2014). "Dong Z and co-workers recently showed that ATRA is able to decrease the expression of interleukin-17A (IL-17A), IL-6, and TGF-β1, and could alleviate bleomycin-induced pulmonary fibrosis in C57BL/6 male mice." (PMID 23344030, 2012). "However, the interaction between IL-17A and TGF-β in development of pulmonary fibrosis remains unclear." (PMID 35739565, 2022). "As we observed previously about IL-17A, mice with comorbidity also showed a significant increase in IFN-γ like A. suum infection, but was not reduced or increased in relation of bleomycin-induced pulmonary fibrosis." (PMID 31765381, 2019).